FGF23 (fibroblast growth factor 23)
Diseases named in the same sentence as FGF23 in open-access papers (continued):
Sharing a sentence is not in itself a finding about the gene and the disease.
uremia (34 papers, 2012 to 2025). A clinical syndrome associated with the retention of renal waste products or uremic toxins in the blood. "In contrast, chronic inflammation associating uremia raises biologically active intact FGF-23 levels because prolonged periods of FGF-23 overproduction exceed the capacity of the FGF-23 breakdown in osteocytes." (PMID 40387920, 2025). "The FGF23–Klotho axis emerges as a new therapeutic target to prevent acquired long QT syndrome in uremia by minimizing the predisposition to potentially fatal ventricular arrhythmias and sudden cardiac death in patients with CKD." (PMID 35042527, 2022). "Unfortunately, the increased secretion of FGF23 associated with uremia also contributes to the cardiovascular risk associated with this syndrome." (PMID 34359914, 2021). "(Acute elevations of Pi do not provoke an increase in plasma FGF23 levels, but the chronic elevations associated with uremia or high-Pi diets are indeed characterized by elevated plasma FGF23." (PMID 34359914, 2021). "In the present study, cardiac Fgf23 correlated with Agt expression in experimental uremia and FGF23 increased expression of RAAS-associated genes in both NRVM and NRCF in vitro, confirming previous work of our research group." (PMID 31540546, 2019). "However, our study only suggests that full‐length FGF23 is involved in the process of myocardial fibrosis caused by uremia." (PMID 36102251, 2022). "Uremia was associated with increased serum FGF23 concentration in the CRF control group." (PMID 26221597, 2015). "In uremia, some studies point out an association between FGF23 and Ca." (PMID 27081473, 2015). "Uremia is characterized by the presence of extraordinarily high levels of FGF23, which may help prevent the Ca loss." (PMID 27081473, 2015). "In CKD patients, dietary restriction and loss of appetite due to uremia or high levels of fibroblast growth factor 23 may be stronger determining factors for 25-(OH) D3 deficiency." (PMID 23878538, 2013). "Furthermore, the amelioration of uremia by dietary Mg supplementation was associated with the total or partial correction of other parameters of mineral metabolism as phosphate and FGF23; abnormal mineral metabolism parameters have been related to the progression of cardiovascular dysfunction." (PMID 36829843, 2023). "We carried out a translational approach to study the relationship between the FGF23–Klotho signaling axis and acquired long QT syndrome in CKD-associated uremia." (PMID 35042527, 2022). "The most important is the lack of determination of more serum inflammation (IL-6, IL-10, IL-18, TNF-α), bone metabolic (FGF-23 and bone alkaline phosphatase), and uremia markers." (PMID 36611532, 2022). "In uremia circulating PTH is necessary for generating the increase in FGF23 expression in bone and the high plasma levels of FGF23, as shown in experimental studies by us and others." (PMID 33233840, 2020). "Secondly, the majority of our patients were at CKD stages 4 and 5 at which the deranged metabolic axis of calcium-phosphate-PTH/FGF23 is well established as are the atherosclerotic changes driven by the progression of uremia." (PMID 32571327, 2020). "Animal and human studies have shown that specific conditions, such as treatment with active vitamin D, phosphate overload, and uremia, upregulate FGF23 transcription in bone and elevate circulating FGF23 concentrations." (PMID 30627598, 2019). "In summary, we demonstrated an activation of endogenous cardiac RAAS in experimental uremia correlating with the progression of LV fibrosis and in response to FGF23 treatment in cardiomyocytes and cardiac fibroblasts in vitro." (PMID 31540546, 2019). "Uremia, metabolic acidosis, an abnormal vitamin D-parathyroid hormone-FGF-23 axis, and an inflammatory milieu are all factors that contribute to a significantly higher risk of fracture in those with kidney disease." (PMID 28460645, 2017).
uremia (continued). "Interestingly, uremia-induced cardiac Fgf23 significantly correlated with endogenous Agt mRNA expression as first parameter of the RAAS pathway." (PMID 31540546, 2019). "The present study showed that experimental uremia and FGF23 stimulation induced the activation of cardiac RAAS promoting LVH and cardiac fibrosis, which could be pharmacologically blocked by losartan and spironolactone in vitro." (PMID 31540546, 2019). "Surprisingly, in uremia, concomitantly elevated FGF23 and PTH levels are observed." (PMID 29063159, 2018). "We have not determined whether the C‐terminal fragment of FGF23 is involved in the process of myocardial fibrosis caused by uremia." (PMID 36102251, 2022). "First evidence that FGF23 may promote LVH came from clinical association studies in CKD patients, which was verified in different rodent models of experimental uremia." (PMID 34778257, 2021). "Taken together, these in vivo results suggest a direct relationship between FGF23, local RAAS and the progression of LV fibrosis in experimental uremia." (PMID 31540546, 2019). "Normally, FGF23 decrease PTH gene expression and parathyroid cell proliferation 64, 65, however, hyperplastic parathyroid glands in uremia patients resist to FGF23 inhibitory action due to low expression of both klotho and FGF 23-receptor complex 66-68." (PMID 31839746, 2019). "Calcitriol continues to stimulate FGF23 expression in uremia and so treatment with active vitamin D analogs in CKD patients may not only target PTH levels but also unwanted FGF23 expression in bone." (PMID 33233840, 2020). "Under physiological conditions FGF23 inhibits PTH secretion and production; however, in uremia, FGF23 fails to inhibit PTH release because of downregulation of the parathyroid FGFR1/Klotho complex." (PMID 30909513, 2019). "In addition, uremia induced suppression of DMP1, and hence increments of FGF23 may explain the clinical observation that in more early stages of CKD, FGF23 and phosphate levels appear to diverge, pointing to another inducer of FGF23 than phosphate itself, namely suppressed DMP1." (PMID 35629904, 2022).
Myocardial fibrosis (32 papers, 2016 to 2026). "Previous investigations associated FGF-23 with causal myocardial fibrosis during acute cardiac injury." (PMID 35622651, 2022). "Studies have found that high phosphate can cause LVH, myocardial fibrosis, and increase the risk of cardiovascular death through the paracrine effect of FGF-23." (PMID 33748139, 2021). "Regarding FGF23-associated myocardial fibrosis, early studies showed that FGF23 promotes the expression of TGF-β in cardiac fibroblasts, which induce cardiac fibrosis through the β-catenin pathway." (PMID 30909513, 2019). "In the present study, we analyzed the association of FGF23 and myocardial fibrosis." (PMID 27579618, 2016). "This study suggests a role of FGF23 in the regulation of myocardial fibrosis, which shows the potential of targeting FGF23 in the treatment of HF and cardiac fibrosis." (PMID 41972542, 2026). "In a murine model of pressure overload CHF induced by transaortic constriction, gene expression of FGF23 and protein expression were upregulated, resulting in myocardial fibrosis and hypertrophy." (PMID 41300756, 2025). "In these models, the mechanism driving FGF23-induced myocardial fibrosis and diastolic dysfunction is mediated by upregulation of genes coding for ß-catenin, transforming growth factor β (TGF-β), procollagen I, and procollagen III." (PMID 41300756, 2025). "Their findings indicate that FGF-23 actually promotes myocardial fibrosis and exacerbates diastolic dysfunction induced by MI." (PMID 37600039, 2023). "Significantly, the endogenous cardiac FGF23 activates paracrine signaling pathways that promote myocardial fibrosis during myocardial infarction or ischemia-reperfusion." (PMID 36835428, 2023). "On the basis of these results, intact fibroblast growth factor 23 promotes CKD‐induced myocardial fibrosis by activating the Shh signaling pathway." (PMID 36102251, 2022). "The CKD model was treated with the glioma 1 (Gli‐1) inhibitor GANT‐61, and myocardial fibrosis and serum intact fibroblast growth factor 23 levels were assessed 16 weeks after nephrectomy." (PMID 36102251, 2022). "In an animal model of experimental hypertrophy that triggers myocardial fibrosis, Fgf23 and Fgfr1 are highly expressed." (PMID 34095143, 2021). "Bacteroides uniformis (Bacteroides genus) was positively correlated with the level of the myocardial fibrosis marker FGF-23 (p < 0.05), while g__Blautia_ASV_5 (Blautia genus) was significantly negatively correlated with FGF-23 and PIIINP level (p < 0.05)." (PMID 34497820, 2021). "In pooled data analysis the myocardial expression of β-catenin positively correlated with dCM (r = 0.74, p < 0.05), myocardial fibrosis (r = 0.69, p < 0.05), and serum FGF23 (r = 0.57, p < 0.05)." (PMID 33924991, 2021). "Our previous reports showed that β-catenin played important role in cardiac or renal fibrosis and FGF23 promoted myocardial fibrosis in post-MI mice mediated by activation of β-catenin." (PMID 33460402, 2021). "Our recent study shows that FGF23 can not only be expressed in cardiomyocytes and fibroblasts, but also promote myocardial fibrosis in mice with MI or ischemia/reperfusion injury." (PMID 33460402, 2021). "In an extension to experimental studies in rats and mice, we recently analyzed the myocardial tissue of CKD patients and investigated cardiac FGF23 expression and myocardial fibrosis." (PMID 29892269, 2018). "Inhibition of β-catenin attenuates FGF23-induced cell proliferation, myocardial fibrosis and TGF- β upregulation." (PMID 30200452, 2018). "This study is attempted to investigate the role of FGF23 in post-infarct myocardial fibrosis in mice." (PMID 27579618, 2016). "In order to clarify the mechanism of FGF23 promoting myocardial fibrosis, we examined the changes of fibrosis-related molecules by Western blotting and Immunohistochemistry." (PMID 27579618, 2016).
Myocardial fibrosis (continued). "Herein, we demonstrated for the first time that FGF23 promotes myocardial fibrosis induced by MI/IR, thus indicating that suppression of FGF23 signaling would be an effective approach to improve myocardial fibrosis." (PMID 27579618, 2016). "Collectively, these data indicate that FGF23 promotes myocardial fibrosis induced by MI or IR through upregulation of TGF-β, procollagen I and III mRNA levels." (PMID 27579618, 2016). "Previous studies have shown that FGF23 promotes myocardial fibrosis." (PMID 36895836, 2023). "Through the stimulation of β-catenin, FGF23 aids in the promotion of myocardial fibrosis." (PMID 36835428, 2023). "This implies that, in the pre-middle-aged hypertensive subjects, exercise training might attenuate myocardial fibrosis which is possibly associated with decreasing AT1R and FGF-23 expression." (PMID 35604403, 2022). "In addition, FGF-23 directly participates in the development of myocardial fibrosis by activating fibroblast growth factor receptor (FGFR)." (PMID 34497820, 2021). "Accordingly, we presume FGF23 might also promote myocardial fibrosis in a FGFR-dependent manner which needs to be investigated in the future." (PMID 27579618, 2016). "Therefore our findings are reasonable that sustained activation of β-catenin by excessive FGF23 promoted myocardial fibrosis in MI/IR mice." (PMID 27579618, 2016). "Interestingly, we found that myocardial FGF23 overexpression promotes myocardial fibrosis both in vitro and in vivo, and these detrimental effects were associated with the accumulation of TGF-β, collagen I and III mediated by the activation of β-catenin." (PMID 27579618, 2016). "Researchers have not clearly determined whether FGF23 plays a role in myocardial fibrosis caused by CKD, despite the findings of recent research." (PMID 36102251, 2022). "On the other hand, FGF23 could lead to myocardial fibrosis through β-catenin and TGF β." (PMID 34992536, 2021). "Therefore, FGF-23 can also be used as a marker of myocardial fibrosis." (PMID 34497820, 2021). "Thus, endogenous cardiac FGF23 synthesis may only impair myocardial fibrosis after MI or ischemia reperfusion through induction of paracrine signaling pathways, including activation of β-catenin and TGF-β." (PMID 29892269, 2018). "Similarly, AAV-sh-β-catenin also attenuated FGF23-enhanced myocardial fibrosis in mice with IR." (PMID 27579618, 2016). "Hence, we aimed to investigate whether FGF23 exerts a direct effect on myocardial fibrosis and then further influences diastolic dysfunction." (PMID 27579618, 2016). "Summary of the results of experimental studies regarding the direct effects of FGF23 on LVH and myocardial fibrosis." (PMID 36909314, 2023). "Summary of the results of experimental studies regarding the indirect effects of FGF23 on LVH and myocardial fibrosis." (PMID 36909314, 2023). "All RAASis reduced PWV elevation, prevented the progression of myocardial fibrosis, and normalized B-type natriuretic peptide, troponin I, and fibroblast growth factor 23 levels without affecting blood pressure." (PMID 38069366, 2023). "In contrast, FGF23 in collaboration with TGFβ1, but not in its absence, induces myocardial fibrosis." (PMID 34095143, 2021). "For instance, Fibroblast Growth Factor 23 (FGF23), a key mediator of salt homeostasis shown to be elevated in high SVI communities and among individuals with high inorganic phosphate intake, has been established as a driver of myocardial fibrosis." (PMID 35004916, 2021). "Nevertheless, blockade of FGF receptors has been shown to improve LVH, myocardial fibrosis and cardiac function and to reduce cardiac mRNA expression of pro-hypertrophic markers (α-MHC, β-MHC, ANP and B-type natriuretic peptide (BNP)) in 5/6 nephrectomy rats with FGF23 excess." (PMID 30200452, 2018).
autosomal recessive hypophosphatemic rickets (30 papers, 2008 to 2026). Autosomal recessive hypophosphatemic rickets (ARHR) is a hereditary renal phosphate-wasting disorder characterized by hypophosphatemia, rickets and/or osteomalacia and slow growth. "Mutations in either PHEX (XLH, X-linked hypophosphatemic rickets) and DMP1 (ARHR, autosomal recessive hypophosphatemic rickets) cause renal phosphate wasting and its clinical sequelae by primary elevations of FGF23." (PMID 35629904, 2022). "For instance, increased serum FGF-23 levels were found in patients with autosomal recessive hypophosphatemic rickets (ARHR), a disease caused by mutation in DMP-1 gene." (PMID 18688277, 2008). "Indeed, a mouse model of autosomal recessive hypophosphatemic rickets (ARHR) with high serum FGF23 levels has reduced skeletal muscle mass and function." (PMID 38791164, 2024).
mineral bone disorder (30 papers, 2012 to 2025). "Fibroblast growth factor-23 (FGF-23) is a bone-derived circulating peptide which has been shown to be associated with early development of CKD-Mineral Bone Disorder." (PMID 29370832, 2018). "Both gain and loss of function mutations in the FGF23 gene result in bone mineralization disorders." (PMID 30971944, 2019). "Systemic levels of FGF-23 are commonly analysed as an important biomarker for the diagnosis and prognosis of mineral bone disorders (MBD), and its measurement is recommended for patients with CKD." (PMID 33767635, 2021). "Recently, we found a strict bone association between Fibroblast growth factor 23 (FGF23) and Fetuin-A, both involved in cardiovascular and mineral bone disorders." (PMID 30791553, 2019). "It has also been described that excess FGF-23 is produced in bone mineralization disorders." (PMID 38720821, 2024). "Additionally, relying on a single time point for FGF23 measurement may overlook dynamic changes in FGF23 levels over time, potentially missing early markers of bone mineralization disorders." (PMID 38951759, 2024). "In CKD patients, parathyroid hormone promotes serum fibroblast growth factor 23 (FGF23) and reduces vitamin D production and activity, resulting in CKD-mineral bone disorder." (PMID 36287917, 2022). "In advanced CKD (stages G4–G5), the strategy focuses on controlling CKD-Mineral and Bone Disorder (CKD-MBD), which is governed by high FGF23 acting as a barrier: High FGF23 actively suppresses the 1α-alpha-hydroxylase enzyme in the kidney, impairing the conversion of 25(OH)D to active 1,25(OH)2D." (PMID 41515987, 2025). "Homeostatic imbalances associated with CKD lead to changes in the regulation of calcium, phosphorous, PTH, fibroblast growth factor 23 (FGF23) and sclerostin levels, resulting in increased bone demineralisation, often referred to as CKD–mineral and bone disorder (CKD-MBD)." (PMID 38541146, 2024). "In addition, a recent study reported that CKD-mineral bone disorder (MBD), phosphorus, and fibroblast growth factor-23 (FGF-23) also affect IR." (PMID 34959901, 2021).